TNFAIP6 (TNF alpha induced protein 6)
Diseases named in the same sentence as TNFAIP6 in open-access papers (continued):
Sharing a sentence is not in itself a finding about the gene and the disease.
Infertility (3 papers, 2018 to 2024). "The expression level of TNFα-induced protein 6 (TNFAIP6) is highly increased in follicular cells, and mutation of TNFAIP6 causes infertility in mice." (PMID 36290198, 2022). "An investigation showed that disruption of TNFAIP6 could cause severe infertility because of defective cumulus expansion and a fault in its organization, which strengthens the idea that optimal expansion of the cumulus mass is crucial for ovulation in mice." (PMID 38419539, 2024).
intervertebral disc degeneration (3 papers, 2020 to 2025). "The current investigation has successfully identified and confirmed an upregulation in TNFAIP6 mRNA expression in individuals with intervertebral disc degeneration (IVDD)." (PMID 39704340, 2025). "In order to validate the potential transcription factor regulatory network, we conducted an analysis of the expression levels of IL-1β, ZEB2, TNFAIP6, and COL6A2 in intervertebral disc degeneration (IVDD) patients." (PMID 39704340, 2025). "Next, an investigation was conducted to determine if ZEB2 acts as a potential key transcription factor in regulating TNFAIP6 and COL6A2 in intervertebral disc degeneration." (PMID 39704340, 2025).
lung adenocarcinoma (3 papers, 2023 to 2026). A carcinoma that arises from the lung and is characterized by the presence of malignant glandular epithelial cells. "Mechanistically, TNFAIP6 interacted with CD44 in lung adenocarcinoma cells, leading to increased extracellular availability of secreted phosphoprotein 1 (SPP1) within the TIME and the subsequent promotion of NETosis." (PMID 41899624, 2026). "We knocked down TNFAIP6 expression in lung adenocarcinoma cells by siRNA and co-cultured neutrophils within its conditioned medium." (PMID 38204755, 2023). "TNFAIP6, as one of these pro-tumor genes, was significantly overexpressed in lung adenocarcinoma cells and might lead to the “N2” polarization of neutrophils in vitro." (PMID 38204755, 2023). "Meanwhile, our in vitro experiments revealed significant upregulation of TNFAIP6 in lung adenocarcinoma cells, which could potentially lead to the “N2” polarization of neutrophils." (PMID 38204755, 2023).
Obesity (3 papers, 2019 to 2023). Accumulation of substantial excess body fat. "MiR-197-3p and miR-23b-3p were downregulated in T2D+ patients with obesity; thus we could expect increased expression of their targets, TNFAIP6, RUNX2, and FBXL13, in these patients." (PMID 31866945, 2019).
colon cancer (2 papers, 2013 to 2024). "Immunohistochemical staining of 55 colon cancer specimens and 50 adjacent normal tissues revealed an increased expression in cancer on a per cell basis, as well as an increase in the frequency of TNFAIP6-expressing cells." (PMID 23536776, 2013). "Here, we investigated the protein levels of TNFAIP6 in colon cancer cells and adjacent normal epithelium." (PMID 23536776, 2013). "Interestingly, lower expression of a number of genes (GREM1, LOX, TNFAIP6, CD36, and EDNRA) predicted better prognosis in both ovarian and colon cancers." (PMID 23536776, 2013).
melanoma (2 papers, 2019 to 2024). A malignant, usually aggressive tumor composed of atypical, neoplastic melanocytes. "Further, analysis of the TCGA datasets of melanoma and pancreatic cancer patients indicated significantly higher expression of TNFAIP6 gene in pancreatic tumors compared to melanoma tumors highlighting the relevance of our finding in human setting." (PMID 38987547, 2024). "In melanomas, genes coordinately expressed with GPC6 were largely those involved in cell adhesion and migration including INHBA, PDGFC, PDGFRA, PPAP2B, SPRX2, TCF4, and TNFAIP6 and ZEB1." (PMID 31199813, 2019).
renal fibrosis (2 papers, 2020 to 2025). A final common manifestation of a wide variety of chronic kidney diseases characterized by glomerulosclerosis and tubulointerstitial fibrosis. "Additionally, the inflammation-related gene TNFAIP6 exhibits significantly altered expression in fibrotic kidney tissues and may serve as a diagnostic indicator of renal fibrosis progression." (PMID 40653823, 2025). "Additionally, generating TNFAIP6-knockout models, if feasible, could help clarify its mechanistic involvement in renal fibrosis and assess its potential relevance in CKD progression and treatment response." (PMID 40653823, 2025).
sarcoma (2 papers, 2021 to 2024). A usually aggressive malignant neoplasm of the soft tissue or bone. "Importantly, 14 genes involved in the interferon gamma response were upregulated including HLA-B, HLA-C, PD-L1, IL2RB and TNFAIP6, suggesting the reprogramming of the immune microenvironment of sarcoma cells on chidamide inhibition." (PMID 33637599, 2021).
systemic sclerosis (2 papers, 2022 to 2025). A chronic disorder, possibly autoimmune, marked by excessive production of collagen which results in hardening and thickening of body tissues. "They found that TNFAIP6 (TNF-α-stimulated gene-6) as a hub gene showed an obvious positive correlation between systemic sclerosis with PH." (PMID 36531719, 2022).
urothelial carcinoma (2 papers, 2021 to 2024). A malignant neoplasm derived from the transitional epithelium of the urinary tract (urinary bladder, ureter, urethra, or renal pelvis). "It has been reported that TNFAIP6 high-expression predicted poor OS in patients with urothelial carcinoma." (PMID 34692520, 2021). "For example, higher expression of TNFAIP6 results into poor prognosis in urothelial carcinomas." (PMID 38376551, 2024).
viral infection (2 papers, 2019 to 2024). "TNFAIP3 and TNFAIP6 have been reported to regulate innate immune response to viral infection." (PMID 39285245, 2024).
adenomyosis (1 paper, 2025). The growth of endometrial tissue inside the muscular wall of the uterine corpus. "Additionally, TNFAIP6 plays a role in immune modulation and tissue repair, processes that are dysregulated in adenomyosis." (PMID 40989079, 2025). "Our transcriptomic analysis identified TNFAIP6, matrix metalloproteinase 7 (MMP7), TNFAIP3, leukemia inhibitory factor (LIF), and serum and glucocorticoid-regulated kinase 1 (SGK1) as the top 5 genes implicated in the inflammatory mechanisms of adenomyosis." (PMID 40989079, 2025).
Arterial thrombosis (1 paper, 2023). The formation of a blood clot inside an artery. "Of these, six genes were most strongly associated with both venous and arterial thrombosis: G0S2, BCL2A1, TNFAIP6 (upregulated), CLIC3, BACH2, and TXK (downregulated)." (PMID 37035297, 2023).
brain tumours (1 paper, 2022). "However, TNFAIP6 expression in brain tumours has yet to be investigated." (PMID 35766985, 2022).
cervical cancer (1 paper, 2021). A primary or metastatic malignant neoplasm involving the cervix. "However, the high expression of CXCL8, TNFAIP6, CXCL5 and CDA in cervical cancer tissues was associated with a poor patient prognosis." (PMID 34174849, 2021).
diabetic foot ulcers (1 paper, 2023). "In chronic wounds, such as healing wounds with diabetic foot ulcers, the fibroblasts overexpress CHI3L1, MMPs, and TNFAIP6, similar to the hub genes in this study." (PMID 37685578, 2023).
ductal carcinoma (1 paper, 2024). "However, the immunohistochemical analysis indicated that TNFAIP6 protein expression intensity was positive in both normal breast tissue and ductal carcinoma." (PMID 39765744, 2024). "This immunohistochemical analysis indicated that TNFAIP6, IFRD1, and IRF6 protein expression intensity was positive in normal breast tissue and ductal carcinoma." (PMID 39765744, 2024).
E. coli infection (1 paper, 2019). "As for the eight common genes screened out in all four datasets, CEACAM1, GK, PFKFB3, and TNFAIP6 emerged repeatedly in the S. aureus group, but CEACAM1, IL18RAP, LILRA5, PFKFB3, PSTPIP2, and SOCS3 emerged in the E. coli infection." (PMID 31093495, 2019).
epithelial dysplasia (1 paper, 2024). "ZSP-M inhibited the degree of epithelial dysplasia in precancerous lesions by inhibiting the expression of the TNFAIP6 and CD163 proteins in the precancerous lesions of the tongue." (PMID 39068492, 2024).
histiocytic sarcoma (1 paper, 2021). An aggressive malignant neoplasm with a poor response to therapy, usually presenting as stage III/IV disease. "TNFAIP6 shows a 10.9-fold increased expression in histiocytic sarcoma cases homozygous for the CFA19 haplotype relative to heterozygous individuals." (PMID 33983928, 2021). "Candidate genes at both loci, PIK3R6 and TNFAIP6, have tumor suppressive and metastatic roles in other cancers, and mutations in members of the PI3K and tumor necrosis factor pathways have been identified in human histiocytic sarcoma and lymphoma tumors." (PMID 33983928, 2021).
Huntington disease (1 paper, 2025). Huntington disease (HD) is a rare neurodegenerative disorder of the central nervous system characterized by unwanted choreatic movements, behavioral and psychiatric disturbances and dementia. "While TNFAIP6 was primarily enriched in the following pathways: FA, huntingtons disease, leukocyte transendothelial migration, mapk signalling pathway and pathways in cancer (Panel C in the Online Supplementary Document)." (PMID 41267622, 2025).
kidney cancer (1 paper, 2008). Primary or metastatic malignant neoplasm involving the kidney. "A highly significant upregulation of TNFAIP6 mRNA expression was observed in kidney cancer in 91% of cases." (PMID 18226209, 2008).
kidney damage (1 paper, 2023). "Also, TLR4, AOC3, IRF4, and TNFAIP6 were not differentially expressed in non-drug-induced AKI models including IRI and UUO models, which was unexpected and additional evidence of the specificity of these hub genes in drug-induced kidney damage." (PMID 37063876, 2023).
leishmaniasis (1 paper, 2016). Infectious disease that is transmitted through the bite of hematophagous female phlebotomine sand flies. "The fact that TNFAIP6 (TSG-6) has not been previously reported in leishmaniasis, and due to the important level of down-regulation found in DCL patients, its role still needs to be analyzed at the functional level." (PMID 27031998, 2016).
lymph node metastasis (1 paper, 2024). "What is more, the higher expression of TNFAIP6 in GC tissues was discovered than that in normal gastric tissues, and its level was positively relevant with lymph node metastasis and TNM stage." (PMID 38376551, 2024).
mastitis (1 paper, 2019). Inflammation of breast tissue during lactation or postpartum due to an obstructed duct or infection. "TNFAIP6 is upregulated in response to many proinflammatory cytokines such as TNF-α and interleukin-1, and elevated levels of TNFAIP6 have been reported in the plasma of both LPS stimulation and S. aureus-induced mastitis." (PMID 31093495, 2019).
mesothelioma (1 paper, 2012). A usually malignant and aggressive neoplasm of the mesothelium which is often associated with exposure to asbestos. "We show in this work that MMP2, BAFF/BLyS/TNFSF13B, RANTES/CCL5 and TNFAIP6/TSG-6 are highly expressed in 3D mesothelioma but not in monolayers." (PMID 22737246, 2012).
metastatic cancer (1 paper, 2020). A carcinoma which has spread from the original site of growth to another anatomic site. "Next, we wanted to determine whether the suppression of TNFAIP6 could block cell migration and invasiveness in active PLK1-driven metastatic cancer." (PMID 31548612, 2020).
oropharyngeal cancer (1 paper, 2025). Carcinoma, predominantly squamous cell, arising from the epithelial cells of the oropharynx. "In relation to oral and oropharyngeal cancer, significant associations were observed for a suite of genes including HSPA5, TNFAIP6, AKR1C1, CASP1, ANXA1, and MYC." (PMID 41023518, 2025).
Osteopenia (1 paper, 2025). Osteopenia is a term to define bone density that is not normal but also not as low as osteoporosis. "Conversely, Grem1, a BMP antagonist, was upregulated in Tnfaip6-deficient mMSCs, in line with its known inhibitory role in osteoblastogenesis and association with osteopenia." (PMID 41394803, 2025).
Peritoneal Fibrosis (1 paper, 2019). Disorder characterized by a wide range of structural changes in PERITONEUM, resulting from fibrogenic or inflammatory processes. "Whereas the role of TNFAIP6 and ZC3H12A in peritoneal fibrosis have not been reported yet, superoxide dismutase 2 encoded by SOD2 is a mitochondrial antioxidant previously known to play a role in protection against peritoneal fibrosis." (PMID 30728376, 2019).
primary immunodeficiency (1 paper, 2022). "TNFAIP6 might be involved in “allograft rejection”, “cytokine-cytokine receptor interaction”, “drug metabolism-other enzymes”, “primary immunodeficiency”, and “T cell receptor signaling pathway”." (PMID 35757392, 2022).
squamous cell carcinoma (1 paper, 2025). A carcinoma arising from squamous epithelial cells. "Because of this, we investigated the correlation between TNFAIP6 and PLK1 expression in LUAD and squamous cell carcinoma (LUSQ)." (PMID 40860188, 2025).
thrombosis (1 paper, 2023). "Recently, dysregulation of the ANXA3, TNFAIP6, TXK, BACH2, and SERPINB2 genes has been associated with both arterial and venous thrombosis in the general population." (PMID 37035297, 2023).
venous thromboembolism (1 paper, 2023). Occlusion of the lumen of a vein by a thrombus that has migrated from a distal site via the blood stream. "We chose to quantify ANXA3, TNFAIP6, TXK, BACH2, and SERPINB2 mRNA expression in t-PAPS based on the results of a meta-analysis using a bioinformatics panel to explore the differences and similarities between venous thromboembolism (VTE) and cardiovascular disease." (PMID 37035297, 2023).
tumor (40 papers, 2008 to 2026). "High TNFAIP6 expression is significantly positively associated with aggressive pathological characteristics, suggesting its roles in tumor development and progression." (PMID 36389748, 2022). "Given that TNFAIP6 is related to inflammation and cancer 9, the expression of cytokines and chemokines was observed in both normal tissues and adjacent tumor tissues of LUAD patients." (PMID 40860188, 2025). "P.g. also manipulates inflammatory signaling in SCC-25 cells by activating NF-κB and MAPK pathways, driving tumor-associated inflammation and metastasis via upregulation of CCL20, TNFAIP6, CXCL8, TNFAIP3, TRAF5, CYP1A1, and NOD2 gene expression." (PMID 40924302, 2025). "In the genomic analysis of LUAD, the levels of TNFAIP6 were higher in patients with advanced stages 2-4 (75%) than in those with tumor stage 1 (66%), indicating that TNFAIP6 and PLK1 were markedly expressed in advanced LUAD." (PMID 40860188, 2025). "Such analysis indicated that the TNFAIP6 gene expression was higher in the tumor than in the normal adjacent tissues." (PMID 39765744, 2024). "Results show that TNFAIP6 expression was significantly (p < 0.05) higher in tumor tissue than in normal tissue." (PMID 39765744, 2024). "The gene transcription of Calr3, Hspb1, and Tnfaip6, which are related to immunogenicity induction of dead cells, was up-regulated in the R2016 treated tumor cells." (PMID 28282460, 2017). "CCL20 and CXCL1 are involved in tumor growth and TNFAIP6 can regulate the growth of smooth muscle cells." (PMID 23028973, 2012). "In early-stage MF, we observed gene expression differences in cells of both the stroma and the immune system, with keratinocytes exhibiting increased interferon response and proliferation (STAT1, ICAM1, HLA-DRA, GJB2), while fibroblasts displayed tumour-associated programs (CXCL2, TNFAIP6, CEBPD)." (PMID 41888970, 2026). "Our results in this study indicated that TNFAIP6 might stimulate the neutrophils’ pro-tumor effects by inducing “N2” polarization." (PMID 38204755, 2023). "Through single-cell transcriptomic sequencing, we discovered that the monocyte_C02 subpopulation is more prevalent in right-sided colorectal cancer, and its highly expressed genes, such as CXCL8, TNFAIP6, CXCL3, and SPP1, may be implicated in tumor growth promotion." (PMID 38711918, 2024). "TNFAIP6, a secreted product of tumor necrosis factor-stimulated gene 6 (TSG-6), plays an important role in tumor prognosis, but its role in LGG needs further validation." (PMID 40130175, 2025). "A heatmap analysis was conducted using a TCGA dataset of LUAD patients for TNFAIP6, PLK1, and mesenchymal markers including CDH2, SNAI1, and SNAI2 in paired normal tissue (left, normal) and adjacent tumor tissues (right, LUAD) depending on stages." (PMID 40860188, 2025). "High variability genes in monocyte_C02 cells, including CXCL8, TNFAIP6, CXCL3, and SPP1, indicate a potential role in tumor promotion." (PMID 38711918, 2024). "Remarkably, we observed clear induction in the expression of marker genes of inflammatory progenitor cells after treatment with tumor cell-conditioned medium, including CCL2, CXCL2, TNFAIP6, and TNFRSFL12a." (PMID 36376273, 2022). "Several angiogenesis-related genes like MMP1, MMP3, SFRP2, CXCL8, SERPINE1 and TNFAIP6 were up-regulated in tumors with necrosis, as identified among genes differentially expressed between tumor samples with and without necrosis." (PMID 26485755, 2015). "Therefore, overexpressed TNFAIP6 in LUAD cancer cells might lead to neutrophils “N2” polarization, which exhibited pro-tumor effects." (PMID 38204755, 2023). "Besides, F3, DCBLD2, and TNFAIP6 were detected at low level in both non-tumor cells and tumor cells." (PMID 36180938, 2022).
tumor (continued). "Moreover, the expression levels of PTX3, TNFAIP6, and TNFAIP8L2 and the genetic alterations of TNFAIP1, TNFAIP6, and STEAP4 greatly impact the clinical outcome of HNC patients, likely by regulating the PI3K-Akt, Ras or other signalling pathways or by regulating tumour immune status." (PMID 34344926, 2021). "But, the OS of MT1M was not statistically significant, while the OS of TNFAIP6 and SIDT2 were not in accordance with expression levels in tumor tissues." (PMID 36092901, 2022).